ENSG00000291006 (novel transcript)
Synonyms: LOC730101
Gene: Long non-coding RNA gene on chromosome 6 (52,664,366 to 52,669,155, forward strand). Ensembl gene ENSG00000291006.
Diseases named in the same sentence as ENSG00000291006 in open-access papers:
ENSG00000291006 is named in the same sentence as 6 diseases in open-access papers, as found by Europe PMC text mining. Sharing a sentence is not in itself a finding about the gene and the disease.
ENSG00000291006 shares sentences with these, for which no sentence is quoted: cancer (1 paper); carotid atherosclerosis (1); lung carcinoma (1); osteosarcoma (1); ovarian carcinoma (1); prostate carcinoma (1).